TNF (tumor necrosis factor)
Diseases named in the same sentence as TNF in open-access papers (continued):
Sharing a sentence is not in itself a finding about the gene and the disease.
myocardial ischemia (123 papers, 2007 to 2025). A disorder of cardiac function caused by insufficient blood flow to the muscle tissue of the heart. "The protective effect of the PPAR-γ agonist on TNF–α and IL-6 was described in earlier studies about forebrain ischemia/reperfusion injury and injury caused by myocardial ischemia/reperfusion." (PMID 35204074, 2022). "Myocardial ischemia is a potent stimulus that causes the activation of MCs in the heart and the release of cytotoxic mediators such as IL-6, TNF-α, and IL-1β." (PMID 34512339, 2021). "Myocardial ischemia/reperfusion can cause an increase in the levels of cytokines such as TNF-α, IL-6, and IL-1β." (PMID 30944548, 2019). "In present study, therefore, we investigated the effect of etanercept as an anti-TNF-α therapy on myocardial ischemia/reperfusion rat model and its underlying mechanisms." (PMID 25260027, 2014). "Further studies showed that the stimulus of cardiac ischemia/reperfusion caused a remarkable increase in the expression levels of interleukin-1β (IL-1β), IL-6, and tumor necrosis factor-α (TNF-α) mRNA in ischemic heart tissue, which was effectively prevented by pretreatment with SIN." (PMID 35837272, 2022). "Myocardial ischemia/reperfusion can cause cytokines such as TNF-α, IL-6, and IL-1β." (PMID 31249649, 2019). "TNF-α can trigger the inflammatory reaction caused by myocardial ischemia-reperfusion." (PMID 25260027, 2014). "Myocardial ischemia induces degranulation of resident mast cells and cleavage of membrane-bound TNF-α by the TNF-α cleavage enzyme (TACE), both causing the immediate release of active TNF-α in the ischemic myocardium to act in an autocrine, endocrine, and paracrine fashion." (PMID 24167735, 2013). "The primary constituent gastrodin mitigates myocardial ischemia–reperfusion injury through increased coronary flow, the suppression of endothelin-1 and pro-inflammatory cytokines (TNF-α/IL-6), oxidative stress reduction, and apoptosis inhibition." (PMID 40723404, 2025). "The dominance of TNFα/NF-κB signaling is consistent with previous reports linking GSK-3α to amplified pro-inflammatory responses in cardiac ischemia conditions." (PMID 40836599, 2025). "Tumor Necrosis Factor-alpha (TNF-alpha) has been identified as the principal cytokine induced by Toll-like receptor 4 (TLR4) in the pathophysiology of myocardial ischemia-reperfusion (I/R) injury." (PMID 40386784, 2025). "The compound effectively inhibited TNF-α, IL-1β, and IL-6 levels in myocardial ischemia–reperfusion models while suppressing necroptosis through transforming growth factor-beta-activated kinase 1 (TAK1) phosphorylation regulation." (PMID 41155644, 2025). "Strong stimulation, such as myocardial ischemia, activates myocardial cells and releases cytotoxic mediators such as IL-6, TNF-α, and IL-1β." (PMID 40298805, 2025). "In myocardial ischemia/reperfusion models, Rg2 treatment significantly inhibited the expression of TNFα, IL-1β, IL-6, and monocyte chemoattractant protein-1 (MCP-1)." (PMID 41155644, 2025). "Myocardial ischemia–reperfusion significantly increased the TNF-α levels in the hearts of rats in the CAO group (lane 2, p < 0.001 vs. sham group)." (PMID 38541636, 2024). "TNF-α, for instance, stimulates the myocardium to release free radicals, leading to cardiomyocyte dysfunction after myocardial ischemia." (PMID 39024234, 2024). "Regarding the setting of recurrent cardiovascular events, studies have shown that TNF-α is upregulated in the myocardium in response to myocardial ischemia and reperfusion." (PMID 39367448, 2024). "The HIIT and IPC treatments significantly reduced the increase in TNF-α levels induced by myocardial ischemia–reperfusion (lanes 3 and 4, p < 0.001 vs. CAO group)." (PMID 38541636, 2024). "To emulate the high levels of TNFα or H2O2 induced early by myocardial ischemia, we then utilized TNFα or H2O2 as stressors in mouse adult cardiomyocytes and assessed the resulting mitochondrial metabolic function." (PMID 38221535, 2024).
myocardial ischemia (continued). "Myocardial ischemia–reperfusion induces ROS synthesis, triggering the release of proinflammatory factors (such as TNF-α, IL-6, IL-1β)." (PMID 38541636, 2024). "As well as cinnamic acid decreased serum levels of CK-MB, LDH, TNF-α, and IL-6, and myocardial ischemia increased serum NO activity." (PMID 37368609, 2023). "Inflammation is recognized as the initial step of myocardial ischemia-reperfusion that leads to increased release of proinflammatory mediators, such as TNFα, IL1β, IL-2, IL-6, and IFN-α." (PMID 36902036, 2023). "Among the compounds for targeting the TNF-α/NF-κB pathway, firstly, isoliquiritigenin was previously demonstrated for attenuating myocardial ischemia reperfusion injury and inhibiting the activity of TNF-α." (PMID 36713834, 2023). "The purpose of this review is to update the current knowledge regarding the involvement of tumor necrosis factor (TNF) and TNF super family (TNFSF) members in myocardial ischemia-reperfusion injury and the possible therapeutic implications." (PMID 36902036, 2023). "The development of myocardial ischemia and reperfusion injury requires inflammation mediated by cytokines (TNF-α, IL-6, and IL-8), the extracellular matrix, and chemokines regulated by NF-κB." (PMID 35164043, 2022). "We introduce new data showing that acute myocardial ischemia and reperfusion injury (IR) increase TNF-a, IL-6, and MMP-9 levels in the LV and renal cortex." (PMID 33782857, 2022). "• Septicemia (sepsis): Myocardial ischemia produced by inflammatory mediators (tumor necrosis factor alpha (TNF-ɑ), interleukins (IL-1, IL-6), and bacterial exo- and endo-toxins." (PMID 36311415, 2022). "Similar to our findings, MT-induced downregulation of TNF and IL-6 has been also identified in a rabbit model of myocardial ischemia." (PMID 35495036, 2022). "Another factor that is correlated with myocardial ischemia is tumor necrosis factor alpha (TNFα) along with its receptor TNFR1." (PMID 35323638, 2022). "Myocardial ischemia significantly increased the mRNA and protein expressions of IL-6, IL-8, TNFα, TGF-β1, MMP2, MMP9, and c-Myc in cMSCs." (PMID 36056383, 2022). "In patients with myocardial ischemia, especially in the acute phase, pro-inflammatory biological factors such as hsCRP, tumor necrosis factor-α (TNF-α), interleukin-6 (IL-6), and interleukin-1β (IL-1β) were significantly increased." (PMID 35252378, 2022). "RES suppression of TNFα improves myocardial ischemia and cardiovascular health in swine and human cardiac cells." (PMID 35164043, 2022). "M1 macrophages expressed TNF-α, iNOS, IL-1β, and IL-6, which induced a strong proinflammatory reaction and contributed to myocardial ischemia-reperfusion injury." (PMID 34094602, 2021). "Myocardial ischemia and HCM share the following elements: calcium, ATP, AMPK, PKA, AKT cross-talking with ERK, glucose, INS, SIRT1 gene encoding sirtuin 1, NF-κB, TNF, reactive oxygen species, inflammatory response, and apoptosis." (PMID 34440529, 2021). "It is known that SIRT1 can inhibit the expression levels of p65, TNF-α, IL-1β, IL-6, iNOS, and other markers related to oxidative stress by regulating the NF-κB pathway, thus playing a role in myocardial ischemia-reperfusion." (PMID 34868528, 2021). "TNF-α-induced caspase-8 activation results in the leakage of RyR2 channels that promote cardiac remodeling after myocardial ischemia/reperfusion." (PMID 33796569, 2021). "The release of inflammatory factors, such as TNF-α, IL-1β, and others, have been found to play important roles in mediating and exacerbating myocardial ischemia/reperfusion injury." (PMID 32116705, 2020). "Another report showed the reduced release of TNF-α, IL-1β, and IL-6 in myocardial ischemia/reperfusion (MI/R) rats treated with MLB." (PMID 33014451, 2020).
myocardial ischemia (continued). "Previous studies have reported that over expression of EH-myomesin (MYOM2 isoform) served as a biomarker for dilated cardiomyopathy and TNF-α was up-regulated during brief myocardial ischemia, or coronary occlusion." (PMID 31195969, 2019). "PLD1 has been shown to be involved in TNF-α expression and release upon myocardial ischemia and reperfusion injury." (PMID 29968773, 2018). "TNF-α, IL-1, IL-6, and IL-8 after myocardial ischemia began to produce and release TNF-α, which exacerbates myocardial injury via activation of neutrophils and endothelial cells." (PMID 26941825, 2016). "A variety of factors other than myocardial stretch have been shown to stimulate secretion of BNP, such as myocardial ischemia, endocrine and paracrine factors such as endothelin, angiotensin II, and TNF-α." (PMID 27478508, 2016). "When myocardial ischemia occurs, vascular endothelial cells are stimulated first; following the activation of NF-κB the expression of a variety of substances, including TNF-α and vascular cell adhesion molecule-1 (VCAM-1), is initiated." (PMID 25667680, 2015). "Despite the appearance of numerous cytokines following myocardial ischemia, the elevation of TNF-α expression was shown to only be apparent during reperfusion." (PMID 25936661, 2015). "It has been reported that hearts from TLR4-defctive mice and TLR4 knockout mice display attenuated NF-κB activation and reduced production of pro-inflammatory cytokine (TNF-α, IL-1β and IL-6) following myocardial ischemia with a short period of reperfusion." (PMID 25823011, 2015). "During myocardial ischemia, TNF- is released from macrophages, monocytes and mast cells and after reperfusion TNF- is expressed and secreted in both cardiomyocytes and fibroblasts." (PMID 25807532, 2015). "Serum TNFα increased from 23 ± 1.5 pg/mL to 180 ± 56 pg/mL following myocardial ischemia (P < .01) when analyzed after reperfusion." (PMID 26430494, 2015). "A prior study showed that when Toll-like receptor 4 was mutated or deficient, the rate of cardiomyocyte apoptosis and the infarct size decreased, with the expression of HMGB1 and TNF-α notably inhibited following myocardial ischemia/reperfusion." (PMID 25780404, 2015). "These authors investigated the effect of CsA after myocardial ischemia with the finding that it was able to decrease the systemic TNF-α level and thereby the progression of generalized inflammatory reaction." (PMID 24968303, 2014). "The Decision Tree building with TNF-α, IL-10, and IL-8 is helpful for the diagnosis of blood stasis syndrome in myocardial ischemia animals." (PMID 24371451, 2013). "We explored a new pattern of biomarkers for blood stasis syndrome with myocardial ischemia, which was a Decision Tree building with TNF-α, IL-10, and IL-8." (PMID 24371451, 2013). "These proinflammatory cytokines (particularly TNF-α), as important factors in cardiac dysfunction, activate neutrophils and endothelial cells and aggravate myocardial ischemia/reperfusion injury." (PMID 23737849, 2013). "The results showed that both citric acid and L-malic acid decreased TNF-α level and inhibited platelet aggregation on myocardial ischemia/reperfusion injury." (PMID 23737849, 2013). "Taken together, TLR2, TLR9, TNF-α and IL-10 were still elevated above control at the onset of cardiac ischemia." (PMID 23929312, 2013). "Alterations of lipid profile, cardiac and inflammatory markers (Il-1β, PTX 3 and TNF- α) were observed in myocardial ischemia group." (PMID 23036047, 2012). "Recently, researchers reported the upregulation of cytokines also in uninvolved tissues—for example, a high expression of TNF-α in the brain following cardiac ischemia and trauma." (PMID 19421412, 2009). "Research has shown that higher levels of circulatory cytokines such as IL-6, IL-8, and TNF-α are closely related to impaired hemodynamics and may contribute to postoperative myocardial ischemia and deteriorated clinical outcomes after cardiac surgery." (PMID 38807202, 2024).
myocardial ischemia (continued). "Besides, myocardial ischemia–reperfusion increased the levels of TNF-α and IL-6 in the serum, and these levels were reduced by OP treatment." (PMID 38589925, 2024). "In the treatment of rats, a model of myocardial ischemia, the alcoholic extract of Tiekuaizi reduced the expressions of interleukin-18 (IL-18), interleukin-6 (IL-6), and TNF-α and was able to protect against myocardial cell injury produced by inflammatory cell infiltration." (PMID 39830344, 2024). "Furthermore, the NF-κB/TNF-⍺ pathway has been shown to play a key part in myocardial ischemia/reperfusion injury and pathological post-infarction cardiac remodeling." (PMID 38058609, 2023). "In addition, since TNF-α is one of the major factors that contribute to myocardial depression in the myocardial ischemia and infarction model, anti-treatment against TNF-α leads to an improvement in the function and attenuation of remodeling." (PMID 36297305, 2022). "Furthermore, valsartan has been shown to inhibit cardiac TNF-α, IL-6, and IL1β production in a rat model of myocardial ischemia." (PMID 35163209, 2022). "Rosmarinic acid has been shown to protect against inflammation and myocardial cell apoptosis during myocardial ischemia/reperfusion injury by activating peroxisome proliferator-activated receptor γ and inhibiting the production of inflammatory cytokines, such as IL-6, TNF-α, and C-reactive protein." (PMID 34484404, 2021). "Moreover, Emodin also improves myocardial ischemia/reperfusion injury via suppression of pro-inflammatory cytokines (TNF-α and NF-κB) and apoptosis (caspase-3)." (PMID 32326191, 2020). "The underlying mechanisms may be via the down-regulation of TNF-α, TGF-β1, IL-1β, Bax, and the up-regulation of Bcl-2, VEGF, Akt and eNOS expression to attenuate myocardial ischemia, enhance neovascularization and cardiac repair." (PMID 31792327, 2019). "The protective effect of safflower injection against isoprenaline-induced acute myocardial ischemia in rats is likely to be related to a decreased inflammatory response mediated by tumor necrosis factor alpha (TNF-α) and interleukin- (IL-) 6 in the heart tissue." (PMID 31198790, 2019). "Additionally, in isoprenaline-induced rats, Granule of BU-XIN RUAN-MAI ameliorated myocardial ischemia by downregulating the inflammatory factor levels of IL-6, IL-1β, and TNF-α." (PMID 31949464, 2019). "It should be noted that TNFα has an ambivalent role in myocardial ischemia/reperfusion injury." (PMID 27819271, 2016). "The activation of NF-κB following myocardial ischemia could induce the production of TNF-α by myocardial tissues in addition to regulating the expression of numerous genes, including IL-1β, IL-6, ICAM-l and VCAM-1." (PMID 25667680, 2015). "In conclusion, administration of QSYQ could attenuate Ameroid constrictor induced myocardial ischemia, and TNF-α and active caspase-3 seemed to be the critical potential target of QSYQ." (PMID 24817898, 2014). "The potential mechanisms might be associated with down-regulated expression of TGF-β1, TNF-α, IL-1β, ASK1, NF-κB Bax, up-regulated expression of Bcl-2 and Gata4, activation of eNOS pathway to ameliorate myocardial ischemia, and enhanced cardiac repair." (PMID 24260217, 2013). "Greater levels of TNF may not be linked to an increased risk of recurrent coronary events in the stable phase after myocardial ischemia (MI)." (PMID 35813433, 2022). "Moreover, diltiazem also reduced myocardial ischemia, endothelia dysfunction and inflammatory responses, as indicated by changes in c-TnI, plasma vWF and ET-1 levels, as well as the myocardial protein expression levels of TNF-α and IL-6." (PMID 24137281, 2013). "Our findings showed that patients with a history of myocardial ischemia showed high expression of IMA, H-FABP, and the inflammatory factors IL-1β, TNF-α, and IL-6." (PMID 40236258, 2025).
myocardial ischemia (continued). "In myocardial ischemia/reperfusion injury in diabetic mice, the inhibition of HDAC6 can reduce myocardial mitochondrial fission by decreasing the level of tumor necrosis factor alpha and recover mitochondrial complex I." (PMID 40377174, 2025). "It has been shown that puerarin reduced the mRNA and protein levels of Tumor necrosis factor-α (TNF-α), interleukin 6 (IL-6), and IL-1β in a mouse model of myocardial ischemia/reperfusion (MI/R) injury, inhibited NLRP3 inflammasome and protected the heart." (PMID 36353499, 2022). "When given before myocardial ischemia, low doses of TNF-a seem to improve myocyte survival, whereas higher doses of TNF-a increase the size of infarction." (PMID 34712629, 2021). "In an animal model of myocardial ischemia, the expression of EGFR in alveolar macrophages was up-regulated, and contributed to the expression of proinflammatory cytokines (such as TNF, IL-6, IL-1β), chemokines (such CXCL2/MIP-2, MCP-1, and CCL3) and iNOS." (PMID 35095926, 2021). "Compared with the sham operation group, the myocardial ischemia-reperfusion injury group showed significant increases in TLR4, NF-KB, IL-1β, TNF-α, and IL-6." (PMID 34093716, 2021). "Tumor necrosis factor-α (TNF-α), caspase-8, and complement component 5a receptor (C5aR) are known to play a crucial role in the myocardial ischemia/reperfusion (I/R) injury in cardiac transplantation." (PMID 32686827, 2020). "It is also reported to attenuate myocardial ischemia–reperfusion by regulating the PI3K/Akt signaling pathway and the subsequent reduction of inflammatory factors, including IL-6, IL-18, and TNF-α." (PMID 28529539, 2017). "Additionally, Rk1 blocks Janus kinase (JAK) 2/STAT3 activation in myocardial ischemia models and reduces STAT1 signaling in TNF-α/IFN-γ-stimulated cells." (PMID 41155644, 2025). "Among them, TNF and IL can inhibit the release of inflammatory cytokines TNF-α and IL-1β, and reduce myocardial cell apoptosis and other damage through SOD-mediated inhibition of oxidative stress, thereby improving myocardial ischemia-reperfusion injury." (PMID 40574818, 2025). "Animal studies have reported that crocetin exerts protective effects against myocardial ischemia reperfusion injury by inhibiting malondialdehyde (MDA) production, blocking tumor necrosis factor-alpha (TNF-α) activity and reducing myocardium apoptosis and infarct size." (PMID 35276955, 2022). "The valerian extract can prevent injuries to myocardial ischemia reperfusion model in the rabbit by decreasing the levels of xanthine oxidase (XOD), malondialdehyde (MDA), and tumor necrosis factor-α (TNF-α), thereby increasing the 6-keto-prostaglandin F1α/thromboxane B2 (6-keto-PGF1α/TXB2) ratio." (PMID 26788113, 2015). "Early studies in isolated perfused hearts undergoing brief myocardial ischemia followed by reperfusion, suggested protective effects of TGF-β, mediated through attenuation of oxidative stress and reduced release of pro-inflammatory cytokines, such as tumor necrosis factor (TNF)-α." (PMID 31620450, 2019). "This led us to the conclusion that the regulation of myocardial cytokines differs from the regulation of serum cytokines, and that at least TNF and IL-1β are not primarily regulated through TLR4 in myocardial ischemia/reperfusion." (PMID 17592640, 2007).